TLR4 (toll like receptor 4)
Diseases named in the same sentence as TLR4 in open-access papers (continued):
Sharing a sentence is not in itself a finding about the gene and the disease.
tumor (continued). "In human CRC, F. nucleatum group infection promotes M2-type macrophage polarization and tumor growth and progression in a TLR4-dependent manner by activating the IL-6/p-STAT3/c-MYC and the TLR4/NF-ĸB/S100A9 signaling pathways." (PMID 41471188, 2025). "The complex interactions between TLR4/MyD88 signaling and tumor progression revealed in our study provide important insights into CRC biology and potential prognostic stratification." (PMID 40703545, 2025). "We believe this is the first report showing that fetuin-A overexpression can upregulate TLR4 expression in these tumor cells." (PMID 40124677, 2025). "Second, TLR4/MyD88 signaling activates the urokinase plasminogen activator system through NF-κB, facilitating tumor invasion and metastasis." (PMID 40703545, 2025). "LPS activates the tumor cell TLR4 signaling pathway and NF-κB, thereby upregulating HIF-1α, promoting the progression of pancreatic adenocarcinoma." (PMID 40529304, 2025). "In this context, taxanes and other chemotherapeutic agents activate the TLR4 signaling pathway in tumor cells, leading to increased VEGFC expression and drug resistance." (PMID 41459512, 2025). "The secreted HMGB1 can enhance the immune response to otherwise poorly immunogenic apoptotic cells by activating a TLR4-dependent, tumor-specific immune response." (PMID 41465435, 2025). "Meanwhile, TLR4 agonists in combination with programmed death ligand 1 (PD-L1) blockers significantly improved the anti-tumor effect, providing a new strategy and experimental basis for combined tumor immunotherapy." (PMID 41568029, 2025). "These patterns of elevated expression further underscore the potential role of TLR4 in modulating immune cell infiltration and shaping the tumour microenvironment composition in PAAD." (PMID 40696496, 2025). "In OS, where the TME is often enriched with immunosuppressive M2-like tumor-associated macrophages (TAM), TLR4 activation emerges as a potent stimulus to reprogram these cells toward a pro-inflammatory, anti-tumor M1 phenotype." (PMID 41516196, 2025). "The relevant literature is hereby summarized to help deepen the understanding of TLR-4-induced tumor resistance and provide potential new strategies for identifying tumor resistance and improving treatment regimens." (PMID 40404908, 2025). "Triple‐negative breast cancer (TNBC), a high degree of malignancy, spatial transcriptomic, and single‐cell RNA sequencing data analyses revealed that the activation of TLR4 in tumor cells enhances the drug responsiveness." (PMID 40727252, 2025). "LPSs can also enhance tumor cell invasion and metastasis through various molecular pathways, including Toll-like receptor 4 (TLR4)/nuclear factor-κB (NF-κB) signaling." (PMID 40722646, 2025). "In cancer treatment, activating TLR-4 can overcome tumor immune tolerance and enhance anti-tumor immune responses." (PMID 40404908, 2025). "The extracellular HMGB1 activates TLR4 on tumor cells to induce EMT‐related genes (e.g., Twist, MMP2, MMP9), enhancing migration/invasion." (PMID 41354099, 2025). "Fusobacterium nucleatum also can promotes colorectal cancer cell proliferation and tumor growth by activating TLR4 signaling to NF-κB and upregulating the expression of microRNA-21." (PMID 39966840, 2025). "We conclude that CD14/TLR4-dependent COX-2 activation is a crucial step in mediating tumor proliferation in response to LPS." (PMID 40444051, 2025). "They found that the TLR-4 expression level was positively correlated with tumor malignancy and chemotherapy resistance." (PMID 40404908, 2025). "Of note, M. elsdenii‐colonized Tlr4−/‐ mice displayed similar weight loss and DAI score while exhibiting identical tumor number and size during the AOM/DSS cycle as that in PBS‐treated Tlr4−/‐ mice." (PMID 40801433, 2025). "Understanding how radiation influences TLR4 expression is critical for deciphering the complex interplay between RT and the tumor microenvironment (TME), particularly in the context of inflammatory signaling." (PMID 41332426, 2025).
tumor (continued). "We found that presence of LPS at subclinical levels, typical for ME, enhances the malignant phenotype of TLR4-expressing BC cells, and in parallel, adversely activates host-derived cells infiltrating the tumor tissue." (PMID 40868123, 2025). "F. nucleatum interacts with TLRs in the tumor microenvironment and activates the TLR4/MYD88/NF-κB signaling pathway." (PMID 40463434, 2025). "Elevated TLR4 expression in tumour cells was correlated with an immunosuppressive environment, positioning TLR4 as a potential therapeutic target." (PMID 40696496, 2025). "Collectively, these findings highlight TLR4's multifaceted role in modulating the immune landscape, promoting tumour immune escape, and advancing cancer progression, thereby reinforcing its potential as a promising target for targeted therapy." (PMID 40696496, 2025). "Previous reports have suggested tumor-promoting effects of endotoxin-elicited TLR4 signaling in “sterile” cancer types (including BC)." (PMID 40868123, 2025). "In parallel, S. bovis can engage TLR2 and TLR4 signaling, driving the recruitment of CD11b+ TLR4+ monocytes to the tumor site, which contributes to local immune suppression and facilitates immune evasion by cancer cells." (PMID 41356485, 2025). "Validation results in in-vitro models suggested that YGS sensitized CRC stem cells via the NF-κB signaling pathway by targeting TLR4 to inhibit tumor immune escape." (PMID 40247422, 2025). "TLR4 activation mediates tumor resistance to cytotoxic T lymphocytes, promoting tumor growth and immunosuppression in vivo and within the TME." (PMID 40762187, 2025). "Sustained activation of pathways such as Janus kinase 2/signal transducer and activator of transcription 3 (JAK2/STAT3) and Toll-like receptor 4 (TLR4) promotes tumor proliferation, invasion, and metastasis." (PMID 41573719, 2025). "Intratumoral microbes upregulate tumor cell PD-L1 expression via LPS-mediated TLR4/MyD88 signaling, reshaping the tumor immune microenvironment, with expression hotspots often corresponding to bacterial aggregation sites." (PMID 40427087, 2025). "In tumor therapy, engineered magnetic microspheres induce TAMs polarization to the M1 phenotype through the TLR4/NF-κB pathway, which reduces the expression of SLC7A11 in tumor cells and thus increases ferroptosis sensitivity." (PMID 40535125, 2025). "In summary, we show that CSF-1, TLR4, and Th2 pathways collectively prepare myeloid–lymphatic progenitors to fuse with tumor LECs, leading to increased proliferation, lymphatic density, and LN metastasis." (PMID 40507286, 2025). "These materials have been shown to activate the cGAS-STING/NF-κB signaling pathway through TLR4, thereby promoting DC maturation and inducing the secretion of IL-6, thus inhibiting tumor growth." (PMID 40432108, 2025). "This suggests that SLAMF8 potentiates the TLR4-NF-κB axis, contributing to an immunosuppressive tumor microenvironment and fostering the conditions for metastatic spread, thereby mechanistically linking this immune checkpoint to aggressive disease." (PMID 41162970, 2025). "Its tumor‐promoting roles are well‐established in colon, liver, pancreas, and skin cancers, but few studies have explored TLR4 involvement in OSCC." (PMID 40762187, 2025). "Vesicles derived from ginseng were reported to reprogram macrophage polarization both in vitro and in vivo via a TLR4-MyD88 signaling pathway, ultimately leading to tumor suppression." (PMID 40648712, 2025). "Recent studies have shown that TLR4/MyD88-mediated COX-2/PGE2 signaling in tumor stromal cells promotes cancer progression through multiple mechanisms: inhibiting apoptosis, enhancing angiogenesis, and modulating immune function." (PMID 40703545, 2025). "To further validate the therapeutic potential of TLR4 in cancer, we evaluated the anti‐tumour effects of the specific TLR4 inhibitor TAK‐242." (PMID 40696496, 2025).
tumor (continued). "For example, TLR4 agonists can enhance ICD in tumor cells; the released TAAs are presented by DCs, activating naïve T cells." (PMID 41488647, 2025). "Since TLR4 expression was found in tumor cells and adjacent non-tumor tissues, mainly in IBC samples, its functional significance merits validation." (PMID 40647480, 2025). "Previous studies have shown that TLR4 promotes tumour progression through activation of pathways such as PI3K/AKT‐NF‐κB in inflammation‐related cancers." (PMID 40696496, 2025). "The pathway’s influence extends to tumor dissemination, with combined high TLR4/MyD88 expression correlating with lymph node metastasis." (PMID 40703545, 2025). "HMGB1, a classic inflammatory damage molecule, is released by dying tumor cells, and DAMPs, which bind to TLR4 or RAGE innate immune receptors on DC cells, mediate innate immune recognition of cancer." (PMID 40524208, 2025). "In particular, the decreased expression of let-7i, a tumor suppressor miRNA, was found to be associated with the ESP-induced upregulation of TLR4 mRNA and protein." (PMID 40732668, 2025). "In contrast, tumors from mice treated with TAK242 in combination with RT showed a marked reduction in TLR4 protein levels compared to RT, confirming that TAK242 effectively suppresses TLR4 in the tumor." (PMID 41332426, 2025). "Western blotting further confirmed that the supernatants from ADVNE− or ADVPPE-treated tumor cells activated the TLR4-MyD88-phosphorylated NFκB-NLRP3 (ASC) pathway in BMDMs." (PMID 40082916, 2025). "Based on our data, we propose a model in which RT activates TLR4 signaling, thereby promoting tumor cell survival and radioresistance." (PMID 41332426, 2025). "Meanwhile, TLR signaling, particularly through TLR2 and TLR4, is activated by microbial components and proinflammatory signals in the tumor microenvironment, recruiting adaptor proteins such as TNF receptor-associated factor 6 (TRAF6)." (PMID 41419456, 2025). "Through suppression of the HMGB1/TLR4 axis, AS-IV reduced M2 macrophage-mediated production of pro-tumor factors such as TGF-β, matrix metalloproteinase 9 (MMP-9), and IL-10." (PMID 40417220, 2025). "In the context of PC, tumor cell expression of IL-1β in vivo was driven by microbial-dependent activation of Toll-like receptor 4 (TLR4) signaling and subsequent engagement of the NLRP3 inflammasome." (PMID 40948749, 2025). "The fusion of M-LECPs with tumor lymphatic vessels has a significant effect on vascular expansion and LN metastasis as shown in MDA-MB-231-tumor-bearing mice treated with a blocker of TLR4." (PMID 40507286, 2025). "For example, in most cancers, uncontrolled TLR4-mdiatd signalling tips the tumor microenvironment (TME) towards a proliferative status, and evasion of immune surveillance; involving secretion of proinflammatory cytokines and other molecules." (PMID 40871563, 2025). "It produces lipopolysaccharides (LPS), which activate the Toll-like receptor 4 (TLR4) and trigger chronic inflammation, thereby contributing to a tumor-promoting microenvironment." (PMID 40641932, 2025). "Expression of TLR4 in tumor cells however varies from one cell type to the other and appears to be under tight regulatory control." (PMID 40124677, 2025). "The release of HMGB1 enhances the immunogenicity of apoptotic cells, and when HMGB1 is secreted by dying tumor cells, it augments tumor-specific immune responses through toll-like receptor 4 (TLR4) signaling." (PMID 39893499, 2025). "Chronic inflammation plays a crucial role, as pro-inflammatory mediators—such as S100A8/A9, tumor necrosis factor-α (TNF-α), and the TLR4-NF-κB signaling pathway—recruit myeloid cells and activate the endothelium, facilitating tumor extravasation." (PMID 40909970, 2025).
tumor (continued). "The TLR4 agonist MPLA upregulates co-stimulatory molecules on DCs, enhances cross-presentation of tumor-associated antigens (TAAs), and promotes CD8+ T cell infiltration." (PMID 41488647, 2025). "Prior research has demonstrated that activating the TLR4/Myd88/NF-κB axis can convert pro-tumor macrophages into tumor-suppressing macrophages, successfully initiating antitumor immune therapy." (PMID 40502627, 2025). "LPS, a gram-negative bacterial outer-membrane component, regulates antitumor immunity via a TLR4-mediated, context-dependent framework, where local concentration and tumor type dictate outcomes." (PMID 41181090, 2025). "Some studies have shown that HMGB1 can inhibit tumor cell growth by interacting with TLR4 and triggering the production of immunosuppressive proteins." (PMID 40969278, 2025). "This was recently demonstrated in preclinical OS models where systemic administration of a detoxified TLR4 agonist inhibited tumor growth and lung metastasis, effects that depended on recruitment and activation of CD8+ T cells." (PMID 41516196, 2025). "S100A8 contributes to the tumor microenvironment by binding to Toll-like receptor 4 (TLR4) and the Receptor for Advanced Glycation End-products (RAGE), activating NF-κB and inducing the production of pro-inflammatory cytokines." (PMID 40963634, 2025). "For instance, in colon cancer (CRC), TLR3 and TLR4 can jointly express chemokines, increase the infiltration of tumor macrophages, and support malignant progression of the tumor." (PMID 40727252, 2025). "TLR4 activation typically promotes pro‐inflammatory signaling, potentially enhancing anti‐tumor immunity through the activation of immune cells such as macrophages and dendritic cells." (PMID 40762187, 2025). "•Stromal cells expressing the transduction factor osterix/sp7 produce fibronectin that acts on a5b1 integrin and/or TLR4 on neighboring fibroblasts to modulate Ly6G+ immune cells and suppress early tumor growth." (PMID 40592236, 2025). "In conclusion, while the TLR-4 signaling pathway holds great potential as a target for overcoming tumor chemotherapy resistance, significant hurdles remain." (PMID 40404908, 2025). "On tumor cells, we have identified TLR4 as the receptor with which fetuin-A interacts to promote tumor growth." (PMID 40124677, 2025). "By knocking down TLR4 on the surface of tumor cells, TLR4 was critical for Escherichia-Shigella- and unclassified_f_Enterobacteriaceae-derived LPS to promote tumor proliferation." (PMID 40817754, 2025). "Increasingly, studies have shown that the inflammatory expression of TLR4 plays an important role in regulating the inflammatory environment around tumors and tumor progression." (PMID 41296391, 2025). "Taken together, these data indicated that stimulation of host TLR4 by microbiota-derived hexa-acylated LPS was required for effective anti-tumour immunity in response to anti-PD-1." (PMID 39929976, 2025). "The disulfide‐linked form of HMGB1 induces VEGF‐A secretion via TLR4, whereas the fully reduced thiol form mediates endothelial cell migration via RAGE, collectively promoting tumor angiogenesis." (PMID 41354099, 2025). "The bacterial metabolite, lipopolysaccharide (LPS), is highly immunogenic and can stimulate tumor progression through TLR4, which subsequently induces phosphatidylinositol-3-kinase (PIK3) and activation of EMT." (PMID 40806562, 2025). "The presence of TLR4 in tumor cells can stimulate tumor development and facilitate the evasion of the immune system by the tumor." (PMID 39708583, 2025). "Following AOM/DSS treatment, Tlr4−/‐ mice exhibited lower weight loss and DAI score, also showed decreased tumor number and size versus WT mice." (PMID 40801433, 2025). "TLR4 downregulation is suggested as a mechanism by which tumors escape from the anti-tumor immune responses." (PMID 40809181, 2025).
tumor (continued). "In TAMs isolated from a tumour cell-injected mouse model, monoacylglycerol lipase (MAGL) KO (and presumably reduced degradation of 2-AG) led to enhanced CB2/TLR4-dependent acquisition of an M2-like phenotype, promoting tumour progression." (PMID 40943579, 2025). "In HCC models, NETs, internalized by tumor cells, trigger a TLR4/9-mediated inflammatory cascade, upregulating cyclooxygenase enzyme 2 (COX-2) and its product, prostaglandin E2 (PGE-2)." (PMID 41516032, 2025). "The study also identified that tumor cell expression of IL-1β is driven by microbial-dependent activation of toll-like receptor 4 (TLR4) signaling and subsequent engagement of the NLRP3 inflammasome." (PMID 39948655, 2025). "Nearly all these proteins were detected in CSF-1 primed myeloid precursors activated by TLR4 or Th2 ligands in vitro and in tumor-recruited M-LECPs in vivo." (PMID 40507286, 2025). "Since HMGB1 can be recognized by TLR4 on immune cells and activate anti-tumor immunity, we used Tlr4-/- mice to block extracellular HMGB1 triggered antitumor immunity." (PMID 40557162, 2025). "Conversely, LPS from Escherichia coli promotes PD-L1 expression in tumor cells via TLR4/NF-κB signaling, contributing to immune evasion." (PMID 40444051, 2025). "For many of these studies, it was assumed that the ligand for TLR4 activation even on tumor cells was the endotoxin, lipopolysaccharide (LPS)." (PMID 40124677, 2025). "The TLR4/MyD88/NF-κB signaling pathway primarily activates and matures DC, boosting the immune system and preventing tumor growth by encouraging cell death." (PMID 41451199, 2025). "In vivo studies demonstrate that the TLR-4-AKT-SOX2 axis within the tumor microenvironment promotes tumor growth." (PMID 40404908, 2025). "We have also reported that uptake of fetuin-A culminating in adhesion in tumor cells was mediated by TLR4." (PMID 40124677, 2025). "Endocytic uptake of Ahsg in tumor cells leads to rapid cellular adhesion and spreading mediated by TLR4." (PMID 39684629, 2024). "For example, TLR4 overexpression in cancer cells can lead to resistance to apoptosis and increased tumor invasiveness." (PMID 39640496, 2024). "Downregulation of TLR4 has been reported to inhibit tumour growth and inflammation, cytokine secretion and to suppress metastasis of carcinoma in several cancers." (PMID 38593176, 2024). "have shown that tumor cells can activate Toll-like receptor 4 (TLR4), which belongs to the pattern recognition receptors (PRRs) family." (PMID 39034996, 2024). "After activation, TLR4 can induce inflammatory signals, promote tumor cell proliferation, and facilitate its escape from immune surveillance, thus promoting tumor metastasis." (PMID 39034996, 2024). "Multiple studies on microbial products and TLR4 agonists emphasize TLR4’s significant role in tumor growth, survival, and progression." (PMID 38930793, 2024). "Gut-derived lipopolysaccharide (LPS) can activate hepatic Kupffer cells, maintaining a pro-inflammatory and tumor-promoting environment via Toll-like receptor 4 (TLR4), which is often overexpressed in HCC tumor tissues." (PMID 39650662, 2024). "CCL17 expression in M2 macrophages can activate Wnt/β-catenin signaling and promote EMT of tumor cells, while tumor cells in turn activate TAMs through the TLR4/TRIF/NF-κB signaling pathway and increase IL-1β production mediated by HIF1α to trigger EMT." (PMID 38957393, 2024). "Toll-like receptor 4 (TLR4) is an endogenous receptor for FN-EDA and has been implicated in regulating tumor growth through its influence on cancer metabolism." (PMID 39286657, 2024). "TLR4 is a tumour stem cell marker and has been found to be upregulated in HCC cells by the secretome of M2 macrophages." (PMID 39684877, 2024). "TLR4-mediated tumor immune escape contributes to neoplastic transformation and cancer progression, linking chronic inflammatory disorders to cancer." (PMID 38930793, 2024).